ANXA10 (annexin A10)
Diseases named in the same sentence as ANXA10 in open-access papers (continued):
Sharing a sentence is not in itself a finding about the gene and the disease.
pancreatic ductal adenocarcinoma (4 papers, 2017 to 2022). An infiltrating adenocarcinoma that arises from the epithelial cells of the pancreas. "ANXA10 expression has been postulated as a useful biomarker for early detection of pancreatic ductal adenocarcinoma since it can be detected in precancerous lesions." (PMID 36247003, 2022). "First, we investigated the possibility of ANXA10 as a serum indicator for pancreatic diseases and evaluated ANXA10 levels in serum of patients with pancreatic ductal adenocarcinoma (PDAC), chronic pancreatitis (CP), intraductal papillary mucinous neoplasm (IPMN), and healthy donors by ELISA assay." (PMID 28369074, 2017). "Of special interest, high ANXA10 expression was reported as an independent poor prognostic biomarker in lung adenocarcinoma, glioblastoma multiforme, serous epithelial ovarian cancer, pancreatic ductal adenocarcinoma, small bowel adenocarcinoma and papillary thyroid cancer." (PMID 36247003, 2022).
adenoma (3 papers, 2019 to 2023). A neoplasm arising from the epithelium. "Furthermore, ANXA10 is significantly downregulated in adenoma from FAP cases compared to FAP controls (FC −2.1, FDR < 0.10)." (PMID 31211760, 2019). "Given its function, ANXA10 expression in adenomas may indicate a protective “gastric programming” that suppresses neoplastic evolution." (PMID 31211760, 2019). "And finally, SNORD123, CEACAM6, SNORD78, ANXA10, SPINK1, and CPS1 genes can be used as biomarkers for normal-adenoma comparison." (PMID 37565794, 2023). "In the adenoma-adenoma comparison, downregulation of several DEGs (CLCA1, ADH1C, ANXA10) in FAP case adenomas was observed." (PMID 31211760, 2019). "ANXA10 is unique in that it is upregulated from normal to adenoma in FAP cases but downregulated from FAP case adenoma to cancer and from FAP control adenoma to FAP case adenoma." (PMID 31211760, 2019). "Within FAP cases, ANXA10 does not differ in cancer-normal but is upregulated in adenoma-normal (FC 2.3, FDR 0.30) and downregulated in cancer-adenoma (FC −1.5, FDR < 0.10) comparisons." (PMID 31211760, 2019).
head and neck squamous cell carcinoma (3 papers, 2019 to 2023). A squamous cell carcinoma that arises from any of the following anatomic sites: lip and oral cavity, nasal cavity, paranasal sinuses, pharynx, larynx, and salivary glands. "The overall goal of this study was to investigate the expression pattern and clinical significance of ANXA9 and ANXA10, specifically in head and neck squamous cell carcinomas (HNSCC)." (PMID 30744186, 2019). "ANXA9 and ANXA10 expression is altered in head and neck squamous cell carcinomas (HNSCC)." (PMID 32824294, 2020). "However, information is lacking on the expression and clinical significance of annexin A9 (ANXA9) and A10 (ANXA10) in head and neck squamous cell carcinomas (HNSCC)." (PMID 30744186, 2019).
liver cancer (3 papers, 2020 to 2024). An epithelial or non-epithelial malignant neoplasm that arises from the liver. "Downregulation of ANXA10 is associated with worse pathological stage and poor prognosis in liver cancer." (PMID 32514252, 2020). "ANXA10 has also been revealed to be low expressed in liver cancer tissue, and its downregulation is related to the malignant phenotype of liver cells, vascular invasion, and HCC progression." (PMID 38365931, 2024).
lung adenocarcinoma (3 papers, 2022 to 2023). A carcinoma that arises from the lung and is characterized by the presence of malignant glandular epithelial cells. "Opposing to this, high ANXA10 expression was detected in lung adenocarcinomas, and promoted the migration of A549 cells." (PMID 36247003, 2022).
ovarian carcinoma (3 papers, 2012 to 2020). A malignant neoplasm originating from the surface ovarian epithelium. "In contrast, ANXA10 mRNA upregulation signified a better prognosis, which was consistent with its correlation with the PFS of all types of ovarian cancer." (PMID 31474227, 2019).
pancreatic cancer (3 papers, 2017 to 2022). "When staining intensity and the percentage of staining cells are considered, annexin A10 can also be used to differentiate intrahepatic cholangiocarcinoma and liver metastasis from pancreatic cancer." (PMID 35227227, 2022). "However, in several studies, it has been suggested that KRT17 and ANXA10 are related to pancreatic cancer." (PMID 30953499, 2019). "The positive ANXA10 expression in stroma which clustered around ANXA10+ ductal cells suggests that ANXA10 may be involved in the tumor-stroma interactions and promote pancreatic cancer development." (PMID 28369074, 2017). "The correlation between ANXA10 expression and the progression of pancreatic cancer remains unknown." (PMID 28369074, 2017). "The correlation of ANXA10 expression with the precursor lesions of pancreatic cancer has not yet been reported." (PMID 28369074, 2017).
papillary thyroid carcinoma (3 papers, 2021 to 2023). "In contrast, the overexpression of the ANXA10 gene significantly inhibits HepG2 cell proliferation in vitro, and its downregulation inhibits papillary thyroid cancer proliferation; it acts directly on TSG101 by inactivating the MAPK/ERK signalling pathway." (PMID 36936694, 2023). "Conversely, in papillary thyroid cancer, the knockdown of ANXA10 promotes apoptosis by inhibiting the MAPK/ERK signalling pathway through the downregulation of TSG101." (PMID 36936694, 2023). "ANXA10 suppresses papillary thyroid carcinoma apoptosis and promotes proliferation by up-regulating TSG101 thereby activating the MAPK/ERK signaling pathway." (PMID 36158697, 2022). "Another study by Liu reported that only ANXA10 of the ANXA family proteins was highly expressed in papillary thyroid carcinoma and was related to papillary thyroid carcinoma differentiation and progression." (PMID 34484309, 2021).
colon adenocarcinoma (2 papers, 2018 to 2022). "Our results demonstrated in univariate analysis that the clinico-pathological and molecular characteristics associated with DDR1 expression in colon adenocarcinoma were: male sex, left colon tumor localization, BRAF wild-type status, and absence of the expression of the serrated marker Annexin A10." (PMID 35205677, 2022).
gastric adenocarcinoma (2 papers, 2017 to 2019). "Previous studies showed annexin A10 expression in the normal gastric mucosa and gastric adenocarcinoma." (PMID 30953499, 2019). "In addition, ANXA10 was expressed in 83% of metastatic pancreatic and 47% of metastatic gastric adenocarcinomas, but was observed in only 2% of metastatic adenocarcinomas from other organs." (PMID 28369074, 2017).
intraductal papillary mucinous neoplasm (2 papers, 2017 to 2025). "In this study, we evaluated the immunohistochemical expression of ANXA10 in a variety of primary human tissue specimens, including normal pancreas, chronic pancreatitis, intraductal papillary mucinous neoplasm (IPMN), PDAC and PanIN tissues from different grades of progression towards PDAC." (PMID 28369074, 2017). "A proteomic study utilized an immunostaining assay to assess annexin A10 (ANXA10) expression in 155 primary human tissue samples, including normal pancreas, CP, PDAC, pancreatic intraepithelial neoplasia (PanIN), and intraductal papillary mucinous neoplasm (IPMN)." (PMID 40619414, 2025).
melanoma (2 papers, 2022). A malignant, usually aggressive tumor composed of atypical, neoplastic melanocytes. "Studies have reported that the expression of ANXA10 is significantly increased in melanoma and can promote melanoma metastasis by suppressing E3 ligase TRIM41-directed PKD1 degradation." (PMID 35693827, 2022). "ANXA10 boosts melanoma metastasis via inhibiting E3 ligase TRIM41-directed PKD1 degradation." (PMID 36158697, 2022).
oral cancer (2 papers, 2012 to 2023). "Given that ANXA10 overexpression may predict malignancy, patient stratification by ANXA10 status may provide a more personalized approach to human oral cancer therapy." (PMID 23029062, 2012). "ANXA10 is frequently found to be highly expressed in human oral cancer, and this high expression may promote G1 phase cell cycle progression by activating the ERK/MAPK signalling pathway, which in turn results in the reduced expression of member-dependent kinases of cell cycle proteins." (PMID 36936694, 2023).
pancreatic adenocarcinoma (2 papers, 2017 to 2019). "The authors demonstrated that ANXA10 was expressed in 78% pancreatic adenocarcinoma and 51% extrahepatic cholangiocarcinoma." (PMID 30953499, 2019). "We also examined ANXA10 expression on the histologically normal tissues adjacent to pancreatic adenocarcinoma." (PMID 28369074, 2017). "We then investigated ANXA10 expression in PanINs, the most common precursor to invasive pancreatic adenocarcinoma." (PMID 28369074, 2017). "Together with the result that CD24 plays an important role in stimulating tumor cell proliferation, the coexpression of ANXA10 with CD24 indicates that ANXA10 may be involved in the early event during the development of pancreatic adenocarcinoma." (PMID 28369074, 2017). "Positive ANXA10 expression was observed in 48 (75%) of 64 pancreatic adenocarcinomas." (PMID 28369074, 2017). "Statistical analysis showed that the coexpression of ANXA10 and CD24 was highly correlated with the progression of pancreatic adenocarcinoma through low- to high-grade PanINs." (PMID 28369074, 2017). "ANXA10 was also negative in the adjacent normal tissue to pancreatic adenocarcinoma and the majority of chronic pancreatitis tissues." (PMID 28369074, 2017). "The co-localization of ANXA10 and CD24 in PDACs and high-grade neoplasia lesions suggests that these two markers may play roles in regulating the progression of pancreatic diseases and the development of pancreatic adenocarcinoma." (PMID 28369074, 2017).
perihilar cholangiocarcinoma (2 papers, 2021 to 2022). "Positive annexin A10 staining was detected for 61 (33%) patients and associated with extrahepatic or perihilar cholangiocarcinoma (p = 0.001) and lower histological grade (p < 0.001)." (PMID 35227227, 2022). "Positive annexin A10 was most commonly detected in extrahepatic and perihilar cholangiocarcinoma; this finding was compatible with that of a previous study." (PMID 35227227, 2022). "Positive annexin A10 staining was more likely to be detected in extrahepatic or perihilar cholangiocarcinoma than intrahepatic cholangiocarcinoma (65% vs. 29%, p = 0.001)." (PMID 35227227, 2022).
prostate carcinoma (2 papers, 2017 to 2023). A carcinoma that arises from epithelial cells of the prostate gland. "Annexin A10 upregulation in prostate cancer downregulates S100A4 expression and the knockdown of S100A4 expression is found to inhibit prostate cancer cell proliferation, migration, and invasion." (PMID 29069865, 2017).
small bowel adenocarcinoma (2 papers, 2022 to 2023). "Expression of annexin A10 was associated with good prognosis of diffuse-type gastric carcinoma, but poor prognosis in intestinal-type gastric carcinoma, papillary thyroid cancer, small bowel adenocarcinoma, and serous epithelial ovarian cancer." (PMID 35227227, 2022).
urothelial carcinoma (2 papers, 2011 to 2019). A malignant neoplasm derived from the transitional epithelium of the urinary tract (urinary bladder, ureter, urethra, or renal pelvis). "We investigated ANXA10 expression by immunohistochemistry using a tissue microarray with 249 Ta and T1 urothelial carcinomas." (PMID 21979422, 2011).
Alzheimer disease (1 paper, 2022). A progressive, neurodegenerative disease characterized by loss of function and death of nerve cells in several areas of the brain leading to loss of cognitive function such as memory and language. "We also found GWAS signals around rs145500243 as follows: rs13133687 (ANXA10), rs538044222 (DDX60L, DDX60), and rs1963569 (DDX60L) were associated with Alzheimer disease (age at onset), BMI-adjusted HC, and energy intake, respectively." (PMID 36276968, 2022).
chronic gastritis (1 paper, 2020). Inflammation of the stomach that is chronic in nature. "The results suggested that the ANXA10 level was significantly lower in early GC samples than in chronic gastritis tissue samples." (PMID 33177783, 2020). "We analyzed the level of ANXA10 in 19 chronic gastritis and 19 early GC samples in GSE55696 using GEO2R." (PMID 33177783, 2020).
chronic pancreatitis (1 paper, 2017). A chronic inflammatory process causing damage and fibrosis of the pancreatic parenchyma. "Only one case of chronic pancreatitis exhibited a moderate ANXA10 expression with less than 10% ANXA10-positive cells." (PMID 28369074, 2017). "However, the staining score of ANXA10 was distinctly increased in IPMNs, PanINs, and PDACs compared to that in normal pancreas and chronic pancreatitis." (PMID 28369074, 2017). "ANXA10 and CD24 positive rates as well as the co-expression rate in normal pancreas, cancer adjacent normal pancreas tissues, chronic pancreatitis, PanINs, IPMNs, and PDACs, respectively." (PMID 28369074, 2017). "The immunofluorescence staining was performed to evaluate ANXA10 and CD24 expression in chronic pancreatitis (CP, n = 5)." (PMID 28369074, 2017). "The ANXA10 staining score (mean (SEM)) in normal pancreas and chronic pancreatitis was extremely low, which was 0.12 (0.12) and 0.80 (0.37), respectively." (PMID 28369074, 2017). "2D plots of ANXA10 and CD24 staining scores in various disease groups, including normal pancreas, chronic pancreatitis (CP), low- and high-grade IPMNs, low- and high-grade PanINs, early- and late-stage PDACs, were generated using SPSS16.0." (PMID 28369074, 2017). "ANXA10 showed no staining or sparse expression in chronic pancreatitis with less than 1% ANXA10+ cells, which was considered as negative." (PMID 28369074, 2017). "The immunostaining result showed that ANXA10 was significantly overexpressed in PanINs, IPMNs, and PDACs but negative in normal pancreas and the majority of chronic pancreatitis tissues." (PMID 28369074, 2017). "However, ANXA10 was absent in ductal epeithial cells in normal pancreas and chronic pancreatitis, where the scores of ANXA10 were assessed in the entire tissue area." (PMID 28369074, 2017). "In summary, ANXA10 was significantly overexpressed in pancreatic ductal epithelial cells of PanINs and IPMNs and tumor cells of PDACs, but negative in normal pancreas and the majority of chronic pancreatitis." (PMID 28369074, 2017). "The receiver operating characteristics (ROC) analysis indicated that ANXA10 expression could distinguish IPMN, PanIN, and PDAC from normal and chronic pancreatitis (AUC = 0.930, 0.931, and 0.941, respectively)." (PMID 28369074, 2017).
colon carcinoma (1 paper, 2014). "Our mining of a microarray dataset of serrated colon carcinoma specimens determined that peptidase inhibitor 3 (PI3), vanin 1 (VNN1) and annexin 10 (ANXA10) are more highly expressed in such cancers as compared to conventional colon carcinomas." (PMID 24533081, 2014).
colorectal tumors (1 paper, 2021). "Certain proteins, such as ANXA10 (Annexin A10), are highly expressed in colorectal tumors, arising through the serrated neoplasia pathway." (PMID 33530449, 2021).
esophageal cancer (1 paper, 2026). A primary or metastatic malignant neoplasm involving the esophagus. "In esophageal cancer, ANXA10 was remarkably down-regulated, and HRG was up-regulated." (PMID 41924732, 2026).
glioblastoma (1 paper, 2024). The most malignant astrocytic tumor (WHO grade IV). "Compared with ANXA1 and ANXA2, which also are overexpressed in glioblastoma, the expression of ANXA10 is lower in glioblastoma." (PMID 38639785, 2024). "ANXA10 was upregulated in glioblastoma, and that correlated with the poor prognosis of the disease." (PMID 38639785, 2024). "Some evidence suggests that ANXA10 could be used as a prognostic biomarker in glioblastoma." (PMID 38639785, 2024).
hepatitis B virus infection (1 paper, 2022). A viral infection caused by the hepatitis B virus. "Positive annexin A10 stating was also associated with lower histological grade (p < 0.001) and less hepatitis B virus infection (p = 0.015)." (PMID 35227227, 2022).
intrahepatic cholangiocarcinoma (1 paper, 2022). A carcinoma that arises from the intrahepatic bile duct epithelium in any site of the intrahepatic biliary tree. "Positive annexin A10 expression was associated with poor prognosis of intrahepatic cholangiocarcinoma." (PMID 35227227, 2022). "In the subgroup analysis, the association between annexin A10 and prognosis was restricted to intrahepatic cholangiocarcinoma." (PMID 35227227, 2022). "The present study revealed that tumor annexin A10 expression was associated with poor prognosis of intrahepatic cholangiocarcinoma, and this association was present in the multivariate analysis adjusting for age, sex, tumor location, tumor grade, hepatitis infection, and disease stage." (PMID 35227227, 2022). "Although annexin A10 staining was positive in only 29% of patients with intrahepatic cholangiocarcinoma, its prognostic influence was strongest for this location relative to other primary tumor locations." (PMID 35227227, 2022). "A recent study reported that annexin A10 expression was associated with poor prognosis for the perihilar and distal cholangiocarcinoma but not for the intrahepatic cholangiocarcinoma." (PMID 35227227, 2022). "By contrast, our study indicated that positive annexin A10 predicted a poor prognosis for intrahepatic cholangiocarcinoma but not for perihilar or distal cholangiocarcinoma." (PMID 35227227, 2022). "Among patients with intrahepatic cholangiocarcinoma, patients with positive annexin A10 staining exhibited significantly poorer survival compared with patients with negative annexin A10 staining (median OS, 2.3 vs. 4.9 years, p = 0.008)." (PMID 35227227, 2022).
metastatic disease (1 paper, 2011). "We showed that low ANXA10 expression was associated with the development of metastatic disease." (PMID 21979422, 2011). "Identification of patients with high risk of micro-metastases by biomarkers as, for example, ANXA10 may facilitate usage of neoadjuvant chemotherapy both as early treatment of metastasis and as treatment of metastatic disease while the burden of disease is low." (PMID 21979422, 2011). "Furthermore, we improved the prognostic value considerably by combining S100A4 with ANXA10 expression, which resulted in a strong and independent prediction of metastatic disease in patients with muscle-invasive cancer." (PMID 21979422, 2011). "Furthermore, combining ANXA10 and S100A4 expression was a highly significant predictor of metastatic disease (P<0.00001, log rank test)." (PMID 21979422, 2011).
Obesity (1 paper, 2014). Accumulation of substantial excess body fat. "From the known functions of these genes, GNAL, HELIOS, and SOX5 are directly related to adipose tissue metabolism or obesity, while SLC9A3, SPOCK3, ANXA10, MYLK, and VSNL1 may be indirectly related." (PMID 24962627, 2014).
oropharyngeal tumors (1 paper, 2019). "Positive ANXA10 expression was found in 64% of tumors, and was significantly associated with differentiation grade (p < 0.001), being also more frequent in oropharyngeal tumors (p = 0.019)." (PMID 30744186, 2019). "Similar to ANXA9, ANXA10 expression was significantly higher in oropharyngeal tumors (p = 0.019)." (PMID 30744186, 2019).
Pain (1 paper, 2024). An unpleasant sensory and emotional experience associated with actual or potential tissue damage, or described in terms of such damage. "This study aims to explore the function and mechanism of LncRNA Anxa10-203 in the development of orofacial neuropathic pain." (PMID 38433184, 2024).
pancreatic disease (1 paper, 2017). "The overall association of disease type with ANXA10 expression yields a p-value less than 0.0001, indicating that ANXA10 expression is strongly associated with pancreatic disease types." (PMID 28369074, 2017). "Correlation between ANXA10 expression and pancreatic disease types." (PMID 28369074, 2017).